CD4 (CD4 molecule)
Diseases named in the same sentence as CD4 in open-access papers (continued):
Sharing a sentence is not in itself a finding about the gene and the disease.
infection (continued). "There was a trend toward higher numbers of splenic CD4+ T cells in IFN-γR−/− mice but not in VAV-Cre+ IFN-γR2flox/flox mice compared with the numbers in WT mice on day 7 of infection." (PMID 28874445, 2017). "Furthermore, a marked reduction in pulmonary Treg (CD4+ CD25+ Foxp3+) cells was observed in IDO1−/− mice at weeks 2 and 10 of infection." (PMID 28791025, 2017). "CD4+ and CD8α+ T cells together with B cells in different organs and blood were investigated by flow cytometry (FCM) for the first time to obtain insights into the local and systemic cellular immune response after vaccination and/or infection." (PMID 28662952, 2017). "Activated CD4+ T cells peak on day 7 post infection but do not return to basal levels again, and sporadic reactivation of CD4+ T cells is observed in R. typhi-infected BALB/c mice." (PMID 28770333, 2017). "Both C57BL/6 MHCI−/− as well as C57BL/6 MHCII−/− mice, that either lack CD8+ or CD4+ T cells are equally resistant to R. typhi, do not show signs of disease and survive the infection." (PMID 28770333, 2017). "This could be due to the fact that the LTBI/HIV+ group exhibited relatively well-preserved CD4 counts and suggests that HIV-induced dysfunction of Mtb-specific cells may only occur at a later stage of infection when HIV pathogenesis is more advanced." (PMID 28848561, 2017). "We here report and characterize a new, THP-1-derived line, THP-1-CD4R, in which CD4 expression is released from miR-221/miR-222 regulatory processes, resulting in high levels of CD4 expression following PMA-induced differentiation, enabling CD4-dependent infection by HIV to efficiently take place." (PMID 29301198, 2017). "In some infections by dimorphic fungi, even in the absence of CD4+ T cells, mice had long-term survival mediated by vaccine-induced IL-17-producing CD8+ T cells." (PMID 28344577, 2017). "In particular, SHIV-#64 infected macaques do not show systemic depletion of CD4+ T-cells after infection because viral replication is suppressed by the host immune response." (PMID 28431573, 2017). "Based on the CD4 counts and years post-infection, infected children were categorized as long-term non-progressors (LTNPs) (n = 20) and progressors (n = 18)." (PMID 29250072, 2017). "There remains, however, a persisting argument that these results reflect macrophages engulfing infected CD4+T cells rather than true infection and replication within macrophages." (PMID 29259605, 2017). "Effector CD4 cells can secrete cytokines after recognition of peptide/MHC complexes displayed on tissue antigen presenting cells, thus targeting inflammatory cytokine production locally to the precise anatomical site of infection." (PMID 28817719, 2017). "Similar to the results of cytokines’ levels, we found that lung CD3+CD4+IFN-γ+, and CD3+CD4+IL-10+ T cells as well as CD11c+SiglecF+IFN-β+ macrophages were significantly increased before and after the infection with S. pneumoniae in HK1505- or PG1505-treated mice when compared to control animals." (PMID 28848552, 2017). "Because the differentiated cells were CD4-negative lineages and because the provirus contained signature inactivating deletions, these results can’t be explained by coincident infection." (PMID 28732051, 2017). "All vaccinated animals with or without directly detectable infection exhibited long term immunological benefits such as reduced rectal CD4 + T cell depletion and highly limited CD8 + T cell hyperactivation." (PMID 28302457, 2017). "Interestingly, while CD4+ T cells from both groups proliferated based on CFSE-staining, the Th2 cytokine IL-4 was reduced in co-infected animals compared to helminth single infection." (PMID 28791259, 2017). "Furthermore, DPG-3 PDDC led to a significant increase of Foxp3 on CD4+ T cells, which was significantly reduced when HIV gp120 treatments blocked DC-SIGN before infection or when cultures were stimulated with LAC." (PMID 28198424, 2017).
infection (continued). "This disease depended on CD8+ T cell evasion by the MuHV-4 K3: when K3 was disrupted, CD8+ T cells achieved long-term infection control and CD4+ T cells were not required." (PMID 28394921, 2017). "Even with this epitope mixture no significant FV-specific CD4+ T cell killing was detected during acute infection." (PMID 28798348, 2017). "Age, timing after infection, phase of the primary infection (acute or early), CD4 and CD8 counts, and HIV-DNA at T0 were not different between groups A and B, while the two patients with no NKG2C+ NK cells showed a trend to lower CD4 counts and higher HIV-DNA." (PMID 28791125, 2017). "During infection, IRF-8 is induced in antigen presenting cells (APC) by IFN-γ and TLR ligands, binds to IRF-4, and stimulates IL-12 as well as IL-18 secretion, resulting in CD4+ Th1 cell differentiation and elimination of intracellular pathogens." (PMID 28968468, 2017). "Although both activated and exhausted CD4 T cells were significantly increased at M2 when compared to HIV-uninfected individuals (P < 0.0001, P = 0.0056, respectively), and slowly but significantly decayed over the first year of infection." (PMID 29354131, 2017). "Depletion studies from one patient confirmed that the T cell responses observed following CCHFV infection in that patient resulted from CD8+ cells rather than CD4+ helper cells." (PMID 29261651, 2017). "Therefore, the cellular immune response evolves during MeV clearance to produce functionally distinct subsets of MeV-specific CD4+ and CD8+ T cells at different times after infection." (PMID 28904342, 2017). "By inhibiting HIV infection of resting CD4+ T cells, these drugs may have the ability to reduce the HIV reservoir size at the beginning of the infection." (PMID 29085362, 2017). "CD4+ T-cell depletion during primary infection by H. capsulatum led to animal’s death, whereas lack of CD8+ T cells decreased fungal clearance." (PMID 28344577, 2017). "parvum antibodies alone cannot clear infection in immunocompromised Cryptosporidium spp.-infected patients without the support of CD4+ T cells." (PMID 29295550, 2017). "Indeed, we did note IFN-γ production by proliferating HEL-specific CD4+ T cells in lymphoid organs (spleen, cervical lymph nodes) in response to MCMV-HEL infection in both sTg-IRBP:HEL mice that had received HEL-specific CD4+ T cells." (PMID 29079770, 2017). "Indeed, infection rates were higher in the overall T cell population (CD3+) and most pronounced, as expected, in the CD4+ cells." (PMID 28953327, 2017). "In conclusion, the CD4+ T cell number and the CD4+/CD8+ ratio were lower in SLE patients with infection compared with patients without infection." (PMID 29267496, 2017). "IFN-γ production by CD4+ T cells was on average but not significantly higher in PFOS treated mice than control at late stage of infection." (PMID 28701769, 2017). "In addition, stimulated CD4 T cells from infected animals produced less IFN-γ and IL-2 at an early time point of infection (21 p.i.)compared to control CD4 T cells." (PMID 28114324, 2017). "Beige mice do not have any reported defect in CD4 T cells or B cells which is reflected in high titers of neutralizing antibodies detected on day 12 post-infection." (PMID 28151989, 2017). "These longitudinal changes observed in the CD4 T-cell compartment over the first year of infection, were not significant for any subset." (PMID 29354131, 2017). "As is mentioned earlier, although it is apparent for the importance of IFN-I on limiting HIV-1 in the acute phase of infection, dysfunctional IFN-I is more likely to disturb the balance of immune system and be detrimental to the function of pDCs, NK cells, CD4+ T cells and Treg in the chronic phase." (PMID 29163506, 2017). "Mice that did not exhibit sufficient percentages of human cells (<65% of CD45+ cells and <70% of CD45+ CD4+ CD3+ cells) were not used in infection studies." (PMID 28880948, 2017).
infection (continued). "However, the proportion of CD4+ and CD8+ T cells were found to be significantly decreased for a few days shortly after PRRSV infection, but returned to pre-infection levels on 8–10 days post infection." (PMID 28278192, 2017). "The highest percentages of both CD4+ and CD8+ within the SMLN of the 1×104 IFU and 1×106 IFU inoculated guinea pigs were recorded upon complete resolution of infection, on dpi21, and were significantly higher (P<0.05) compared to those of non-infected controls." (PMID 28678871, 2017). "A3G/F have been considered as innate immune agents, because they are constitutively expressed in CD4+ T lymphocytes, macrophages, and dendritic cells regardless of infection status, though inflammatory cytokines can upregulate their expression post-infection." (PMID 28893290, 2017). "CD3+/CD4+ T helper cells did significantly increase without infection over course of time after surgery but did significantly decrease in a postsurgical infection scenario." (PMID 29348965, 2017). "After effector CD4+ T cells recognize peptide/MHC complexes displayed on tissue APCs, they can secrete cytokines, and the inflammatory cytokine production is thus targeted locally to the precise anatomical site of infection." (PMID 29261164, 2017). "In vivo TF inhibition by Ixolaris resulted in reduced IA/INFL and hypercoagulation in SIVsab-infected PTMs independent of CD4 counts and plasma viremia and improved the outcome of the SIVsab infection." (PMID 28953320, 2017). "Thus CD4+ and CD8+ T cells co-operated, but less through classical help than through recognizing distinct components of a complex infection." (PMID 28394921, 2017). "Although activated MDDCs are resistant to the infection and do not produce new viral progeny, they can efficiently transfer captured viruses to activated CD4+ T cells that get then productively infected." (PMID 29250073, 2017). "Infection did not affect the percentages of CD4+ T cells positive for interleukin-4 (IL-4) or the activation marker CD69; however, it increased percentages of IL-17A+ CD4+ T cells by 4.0-fold." (PMID 28442605, 2017). "Donors were traced by congenic markers and the CD45.1+CD45.2+:CD45.1−CD45.2+ ratio in peripheral blood was 1:1 and similar proportions of CD4 and CD8 T cells could be detected prior to infection." (PMID 28747914, 2017). "In the second phase, we determined whether procaspase 8-inducing drugs decreased HIV DNA and/or replication in an acute, in vitro infection model using laboratory adapted HIV and primary CD4 T cells." (PMID 28628632, 2017). "Given that total PBMC numbers expanded 14 days after acute (D14pi vs D7pi) and secondary infections with BTV (D42pi vs D28pi and D56pi vs D70pi), we examined whether an increase in CD4+ or CD8+ T cell populations could explain this expansion." (PMID 28662714, 2017). "During natural infection, HIV envelope glycoproteins (gp120 and gp41) are present as trimers on the surface of viral particles, and their binding to cell receptor CD4 and coreceptors (CCR5 or CXCR4) is essential for virus entry into CD4 + T lymphocytes, monocytes and macrophages." (PMID 28842659, 2017). "CD4 T cells and cytokines derived from these cells, such as IFN-γ and TNF, have pleiotropic antiviral effects and are essential for the control of viremia in LCMV Cl13 infection." (PMID 28747914, 2017). "Delayed infection was most correlated with ADCP of the challenge SHIV, but prechallenge levels of peak ADCC titres, Env binding, CD4 and CH01 blocking and infected-cell binding all significantly correlated with time to infection (P<0.05; Spearman rank correlation)." (PMID 28593989, 2017). "At day 6 post infection, ruxolitinib and tofacitinib (0.1, 1.0, and 10 μM) significantly (p < 0.05) reduced extracellular p24 production as well as the frequency of HIV-GFP+ CD4+ cells." (PMID 29267399, 2017).
infection (continued). "Using the FIV model, it has been previously demonstrated that FIV infection phenotypically and functionally activates CD4+CD25+Foxp3+ Treg cells during both the acute and chronic stages of infection and these cells are capable of inhibiting CD4+ and CD8+ T cell effector responses." (PMID 29056671, 2017). "The preferential infection and depletion of CCR6+CD4+ T cell subsets may initiate or contribute to the failure of the gut mucosal immune system." (PMID 28509877, 2017). "The dynamics of CD4+ T cells were not significantly different over time between persistent-infection and controlled-infection granuloma-like structures." (PMID 27799331, 2017). "We found that both groups showed reductions in rectal CD4 + T cells (P < 0.05, Wilcoxon Signed Rank Test on all animals), including the animals without detectable infection, but the relative level of depletion was more pronounced in the controls (P < 0.05)." (PMID 28302457, 2017). "Activation of Rac1 by HIV signaling has been previously reported; however activation of Cdc42 by HIV-1 signaling in CD4 T cells and its role in promoting infection has not previously been demonstrated." (PMID 28114951, 2017). "IFN-γ is a key effector of CD4+ Type 1 and CD8+ T cell, it can activate macrophages and dendritic cells, stimulate increased expression of MHC–peptide complexes, and defend against the intracellular infection." (PMID 28069101, 2017). "Given the features of T. gondii being an intracellular parasite, specific cellular immune response, particularly, a specific T lymphocytes activation (CD4+ T cells and CD8+ T cells) can play a vital role in the alleviation or control of spreading and development of T. gondii in infection." (PMID 28592247, 2017). "However, the infection induced expression of activation and co-stimulatory molecules, ICOS and CD40L, on CD4+ T cells, known to be crucial for T-B interactions providing help for B cell activation, maturation and antibody production." (PMID 28700710, 2017). "As nonimpaired CD4 and T-cell immunity is important for protection of patients from infection with C. jejuni perhaps OPV provides for a more robust cross-reactive T-cell response that helps in clearance of C. jejuni." (PMID 28444240, 2017). "After infection with Listeria monocytogenes (LM) expressing ovalbumin (OVA), OT-I OVA-specific CD8+ T cells secrete higher amounts of CCL3 and CCL4 than OT-II OVA-specific CD4+ T cells immunized simultaneously." (PMID 28686740, 2017). "Interestingly, CD4 depleted animals showed higher viral transcripts at the infected sites when compared with CD8 depleted animals indicating CD4 T cells might have helped to eradicate the infection in these animals by producing neutralizing antibodies to block the viral spread." (PMID 29208932, 2017). "In contrast, depletion of CD8+ or CD4+ T cells, either individually or in combination, did not significantly alter protection against re-infection amongst mice with prior infection." (PMID 29145516, 2017). "CD4+ and CD8+ T cells both help to contain these infections, but disease occurs mainly when CD4+ T cells are lacking, implying that they have particular importance." (PMID 28394921, 2017). "CD4 T cells play an important synergistic role and provide essential help to CD8 T cells, which is the primary effector population responsible for maintaining the chronicity of infection." (PMID 29163509, 2017). "When we looked at total memory CD4+ and CD8+ T cells, it was found that total CD4+ T cells of NT women showed a significantly higher percentage of IL-7Rpos cells, at only one month after infection onset." (PMID 29112951, 2017). "In agreement with the gene expression analysis, at day 28 post-infection, the number of total CD8+ T cells as well as Mtb-specific CD8+ T cells (CD8+ CD44+ TB10.4+) in perigonadal fat increased while the number of CD4+ T cells remained unaltered in contrast to the lung." (PMID 29040326, 2017).
infection (continued). "Here, it seems that antibodies that are produced in the absence of CD4+ T cell help as it is the case in the early phase of infection are less protective than antibodies generated with T cell help." (PMID 28770333, 2017). "While infection did not dramatically alter the overall proportion or number of total CD4+ and CD8+ T cells in the blood over time with either route of infection, we observed the induction of a T cell response that peaked at day 7 post-infection." (PMID 28231312, 2017). "Moreover, CD4+ T cell activation is altered, to a relatively small degree, only in the brains of IFN-γ KO mice during infection." (PMID 28874445, 2017). "Additionally, the numbers of CD4+ cells, neutrophils and eosinophils on the 3 days and CD8+ cells on the 7 days post-infection were higher in the asthmatic/A(H1N1)pdm09 group than other groups respectively, but not statistically." (PMID 28831046, 2017). "Intriguingly, our past studies identifying MCMV epitope-specific CD4+ T cells found that some responses did not expand until much later times following infection, after systemic replication was controlled and persistence had been established." (PMID 28647908, 2017). "Thus Ad5-F or Ad5-H vaccination in sheep induced CD4+ and CD8+ T cell responses that are directed to several epitopes presented also during the course of a natural PPRV IC’89 infection." (PMID 29157291, 2017). "We show that CD4 IL10 production is associated with high-parasite antigen burden, consistent with other infections as well as non-infectious disease models." (PMID 29097996, 2017). "The expansion was followed by a contraction phase in the liver similar to MCMV specific non-inflationary CD8+ and CD4+ T cell responses, whereas splenic Treg cells were maintained at high numbers even 3 weeks after infection." (PMID 28448566, 2017). "ZIKV-specific cytokine production by CD4+ and CD8+ T cells was identified in both PBMC and lymph nodes of ZIKV-infected NHP at multiple time-points post-infection with peak responses noted on day 28 post-infection." (PMID 28608813, 2017). "The gene expression of the T-helper cell specific Cd4 marker was slightly but not significantly increased, whereas the cytotoxic T cell specific marker Cd8 was 47-fold increased 7 days after infection and 5-fold increased after 28 days after infection." (PMID 28352641, 2017). "T cells from CD4+ and CD8+ lineages are essential to control bradyzoites containing cysts at the brain, T cells expressing MMP-10 are present at the brain after 21 days of infection, while T cells expressing MMP-8 are observed at 28th day of infection." (PMID 28955329, 2017). "Consistent with what was found in spleen tissue at 28 days post-infection, the transcription factor Foxp3, showed no increase in mRNA or protein in splenic CD4+ T cells at this time point." (PMID 28103263, 2017). "Early during infection, nonconventional iNKT cells and γδ T cells are the main source of GM-CSF, a role subsequently assumed by conventional CD4+ T cells as the infection progresses." (PMID 29066547, 2017). "DCs can bind, preserve, and transfer infective virions to CD4+ lymphocytes, which might facilitate HIV-1 dissemination both at the mucosal sites of infection and inside peripheral lymphoid tissues." (PMID 28348557, 2017). "In contrast, adoptively transferred Rag2 KO mice that were not infected retained their full quiescent HSPC pool, indicating that infection rather than homeostatic expansion of CD4+ T cells is required to drive LT-HSCs out of quiescence." (PMID 28671989, 2017). "The data clearly showed that adding intranasal immunization to the parenteral immunization led to a strong post-infection increase in both the Th17 (CD4+CD44+IL-17+) and Th1 (CD4+CD44+IFNγ+) response as well the IgA response compared to the pre-infection response." (PMID 28414746, 2017).